ARFIP2 (ARF interacting protein 2)
Description:
Plays a role in constitutive metalloproteinase (MMP) secretion from the trans Golgi network. May have important functions during vesicle biogenesis at certain cargo subdomains, which could be predominantly utilized by secreted MMPs, such as MMP7 and MMP2. Also involved in autophagy by regulating the starvation-dependent trafficking of ATG9A vesicles which deliver the phosphatidylinositol 4-kinase beta (PI4KB) to the autophagosome initiation site. Involved in phagophore growth during mitophagy by regulating ATG9A trafficking to mitochondria. In addition, plays a role in NF-kappa-B inhibition by interacting with IKBKB and IKBKG.
Synonyms: POR1
Tractability: Small molecule: a structure with a bound ligand is known. Antibody: its Gene Ontology location is reachable by antibodies, with high confidence. PROTAC: ubiquitination databases record sites on it; its protein half-life has been measured.
Gene: Protein-coding gene on chromosome 11 (6,474,683 to 6,481,479, reverse strand). Ensembl gene ENSG00000132254.
Subcellular location: Golgi apparatus; Golgi apparatus, trans-Golgi network membrane
Subcellular location (Human Protein Atlas): Golgi apparatus; Nucleoli; Nucleoplasm
Pathways (Reactome):
Vesicle-mediated transport: Retrograde transport at the Trans-Golgi-Network
Gene Ontology:
Molecular function: cadherin binding; GTP-dependent protein binding; identical protein binding; membrane curvature sensor activity; phosphatidylinositol-4-phosphate binding; protein binding; GTP binding; phospholipid binding; small GTPase binding; protein domain specific binding
Biological process: actin cytoskeleton organization; mitophagy; protein localization to phagophore assembly site; intracellular protein transport; lamellipodium assembly; regulation of Arp2/3 complex-mediated actin nucleation; ruffle organization; small GTPase-mediated signal transduction; intracellular protein localization
Cellular component: cell cortex; cytoplasm; Golgi apparatus; ruffle; trans-Golgi network membrane; cytosol; plasma membrane
Genetic constraint (gnomAD): Loss-of-function variants: 14 observed, 40.3 expected, observed/expected ratio (o/e) 0.35, 90% interval 0.23 to 0.54. The upper end of that interval is the gene's LOEUF score, 0.54, which puts it in group 2 of 6, group 1 being the genes least tolerant of losing a copy. Missense variants: 305 observed, 445.32 expected, observed/expected ratio (o/e) 0.68, 90% interval 0.62 to 0.75. Synonymous variants: 167 observed, 182.04 expected, observed/expected ratio (o/e) 0.92, 90% interval 0.81 to 1.04.
Homologues: Orthologues: chimpanzee ARFIP2 (99% identical), macaque ARFIP2 (99% identical), dog ARFIP2 (99% identical), rabbit ARFIP2 (99% identical), guinea pig ARFIP2 (99% identical), mouse Arfip2 (99% identical), rat Arfip2 (99% identical), pig ARFIP2 (99% identical), zebrafish arfip2b (77% identical), zebrafish arfip2a (74% identical), Drosophila melanogaster Arfip (47% identical), Caenorhabditis elegans F54C8.7 (28% identical). Paralogues in human: ARFIP1 (58% identical), PICK1 (25% identical).
Diseases named in the same sentence as ARFIP2 in open-access papers:
ARFIP2 is named in the same sentence as 21 diseases in open-access papers, as found by Europe PMC text mining. Sharing a sentence is not in itself a finding about the gene and the disease. The quoted sentences say what the papers report.
breast carcinoma (1 paper, 2024). "cg17242362 (ATXN7L1) and cg17403702 (ARFIP2) were hypomethylated in breast cancer alone." (PMID 38336771, 2024).
diabetic nephropathy (1 paper, 2024). "We hypothesize that Arfip2 deficiency mediates the dysregulation of mitophagy and autophagy in diabetic nephropathy, leading to cellular dysfunction, inflammation, fibrosis, apoptosis, senescence, and renal hypoxia." (PMID 38247505, 2024).
Glomerular sclerosis (1 paper, 2024). Accumulation of scar tissue within the glomerulus. "This explains how impaired autophagy in Arfip2-deficient diabetic mice promotes glomerulosclerosis and more proteinuria." (PMID 38247505, 2024). "In semi-quantitative index analyses of glomerulosclerosis, we could not observe significant differences between diabetic Arfip2 KO mice and diabetic heterozygous littermates." (PMID 38247505, 2024).
hepatocellular carcinoma (1 paper, 2024). A malignant tumor that arises from hepatocytes. "A high ARFIP2 expression correlates with the early recurrence and metastasis in hepatocellular carcinoma (HCC) patients, while a low expression of ARFIP2 inhibits HCC cell invasion and migration." (PMID 38247505, 2024).
lung carcinoma (1 paper, 2021). "So far, rs2253104 in ARFIP2 has been associated with lung cancer." (PMID 34259936, 2021).
melanoma (1 paper, 2021). A malignant, usually aggressive tumor composed of atypical, neoplastic melanocytes. "Interestingly, ARFIP2 was among the downregulated genes in human melanoma cells treated with arbutin, which is a known inhibitor of melanin biosynthesis used in cosmetology for skin whitening." (PMID 34259936, 2021).
Salmonella Infections (1 paper, 2025). Infections with bacteria of the genus SALMONELLA. "We also investigated the effects of ARFIP2 loss in Salmonella infection." (PMID 40460835, 2025).
type I diabetes (1 paper, 2024). "For the in vivo analyses of Arfip2 deficiency, we used a mouse model of Streptozotozin-induced type I diabetes and investigated physiological data and (patho)histological (ultra)structural modifications." (PMID 38247505, 2024).
infection (3 papers, 2014 to 2025). The state of being infected such as from the introduction of a foreign agent such as serum, vaccine, antigenic substance or organism. "Overall, these data support a role for ATG9A and PI4K2A recruitment to the site of pathogen infection to mediate membrane repair and restrict pathogen infection and a regulation of these events by ARFIP2." (PMID 40460835, 2025).
tumor (2 papers, 2022). "High expression of ARFIP2, SH3GL2, and SRGAP3 help maintain cell tension and stiffness as well as inhibit tumor invasion and metastasis." (PMID 36408514, 2022).
bacterial infection (1 paper, 2025). "Our results identify a role for mobilized ATG9A vesicles and ARFIP2 in lysosome homeostasis after damage and bacterial infection." (PMID 40460835, 2025).
ARFIP2 also shares sentences with these, for which no sentence is quoted: adenocarcinoma (2 papers); carcinoma (1); diabetes (1); endometriosis (1); gastric adenocarcinoma (1); HIV-1 infection (1); metastatic tumor (1); Obesity (1); tumours of the stomach (1); type 2 diabetes (1).